RN7SL272P (RNA, 7SL, cytoplasmic 272, pseudogene)
Gene: Miscellaneous RNA gene on chromosome 13 (27,989,296 to 27,989,584, reverse strand). Ensembl gene ENSG00000242360.
Homologues: Orthologues: chimpanzee Metazoa_SRP (99% identical). Paralogues in human: RN7SL1 (83% identical), RN7SL3 (83% identical), RN7SL2 (82% identical), RN7SL296P (80% identical), RN7SL679P (80% identical), RN7SL126P (80% identical), RN7SL220P (80% identical), RN7SL45P (79% identical), RN7SL230P (79% identical), Metazoa_SRP (79% identical), RN7SL127P (79% identical), RN7SL7P (79% identical), and 702 more.